EZH2 (enhancer of zeste 2 polycomb repressive complex 2 subunit)
Diseases named in the same sentence as EZH2 in open-access papers (continued):
Sharing a sentence is not in itself a finding about the gene and the disease.
insulinomas (5 papers, 2017 to 2025). "Most insulinomas exhibit concurrent mutations in multiple chromatin regulators, particularly in the Polycomb and Trithorax Group genes (such as EZH2, YY1, RING1, BMI1, MEN1, KMT2C and KDM6A)." (PMID 40612435, 2025). "Majority of human insulinomas harbor concurrent mutations of multiple chromatin modifiers including mutations in PcG (EZH2, YY1, RING1, BMI1) and TrxG (MEN1, KDM6A) genes, and often involve copy number gain for one or more PcG proteins." (PMID 35602600, 2022). "EZH2 overexpression appears in most insulinomas, likely driving hyperproliferation and altered gene expression." (PMID 40612435, 2025). "Comparison of gene-expression signatures of proliferating juvenile human and mouse beta-cells with insulinomas revealed EZH2 as a key regulator of juvenile beta-cell proliferation along with PcG-target CDKN1C (encodes cell-cycle inhibitor p57Kip2)." (PMID 35602600, 2022). "The EZH2 locus was found amplified in a subset of insulinomas, and overexpression of EZH2 was reported to induce replication of human beta cells as well as other normal islet cells." (PMID 34638497, 2021). "EZH2 upregulation in some insulinomas may arise from the increase in copy number at the EZH2 locus on chromosome 7q." (PMID 28974674, 2017). "For example, what drives the near universal EZH2 overexpression in insulinomas?" (PMID 28974674, 2017). "A previous study reported dysregulation of epigenetic factors including genomic amplification of EZH2 and overexpression of EZH2 promoted CCND1-induced proliferation of insulinoma cells in human, whereas declined functions of these factors with aging were previously reported in mice." (PMID 33294783, 2020).
invasive carcinoma (5 papers, 2012 to 2024). A carcinoma that is not confined to the epithelium, and has spread to the surrounding stroma. "Here we show that in human invasive carcinomas and distant metastases, cytoplasmic EZH2 phosphorylated at T367 is significantly associated with ER- disease and low H3K27me3 levels." (PMID 30022044, 2018). "Using paraffin embedded sections, total RNA was successfully extracted from 20 IPMN lesions (borderline IPMN in 9, CIS in 6, invasive carcinoma in 5) and 7 pancreatic normal ducts, and then levels of EZH2 and p27Kip1 mRNA were analyzed by real time PCR." (PMID 25084021, 2014). "EZH2 has been detected in a variety of neoplastic cells of poorly differentiated invasive carcinomas." (PMID 23226446, 2012). "Whereas EZH2 nuclear expression was negative in the normal pancreatic ductal cells, EZH2 expression in IPMN lesions increased during IPMN progression, particularly from borderline atypia to invasive carcinoma." (PMID 25084021, 2014).
metastasis (5 papers, 2016 to 2024). The spread or migration of cancer cells from one part of the body (where they first appeared) to another. "EZH2 was positively correlated with clinical stage (P = 0.015) and lymph node metastasis (P = 0.044)." (PMID 26848980, 2016). "The expression levels of EZH2 were elevated in parallel with tumour stage (p = 0.001) and tumour grade (p = 0.001) and were increased in cases with lymph node metastasis compared with node-negative cases (p = 0.018)." (PMID 30542123, 2018).
Myocardial fibrosis (5 papers, 2021 to 2025). "Cardiac-conditional EZH2 deficiency causes severe cardiac defects, including persistent hypertrabeculation, right ventricular hypoplasia, atrial and ventricular septal defects, myocardial fibrosis, and moderately impaired left ventricular systolic function." (PMID 34768802, 2021). "NOTCH1 inhibition decreased myocardial fibrosis and infarction area, while EZH2 inhibition increased fibrosis." (PMID 39951437, 2025). "This study aimed to investigate the effects of the CaN/NFATc3 pathway in DM-related myocardial fibrosis and to clarify the relationship between the CaN/NFATc3 pathway and EZH2 in DM-related myocardial fibrosis in vitro and in vivo." (PMID 37735624, 2023). "In the present study, we also observed that EZH2 inhibition is at least partially responsible for the mitigating effects of MSC-EXO on myocardial fibrosis and EMT." (PMID 35264108, 2022). "It was found by Masson’s staining that MSC-EXO restored myocardial cell alignment in rats, while EZH2 exacerbated myocardial fibrosis." (PMID 35264108, 2022). "In rat myocardial fibrosis, lncRNA MALAT1 binds to the enhancer of zeste homolog (EZH2) and promotes EZH2 activity in the nucleus of cardiomyocytes." (PMID 39113708, 2024).
NK/T-cell lymphoma (5 papers, 2018 to 2025). "Coactivation of PRC2 proteins (EZH2, SUZ12, and EED) were reported to be associated with inferior OS in NK T cell lymphoma." (PMID 29415665, 2018). "In NK/T-cell lymphoma, EZH2 directly activates CCND1 transcription independent of methyltransferase activity." (PMID 34376807, 2021).
skin cancer (5 papers, 2013 to 2025). "We have recently showed that Ezh2 level is increased in epidermal squamous cell carcinoma and is required for skin cancer cell survival, a finding that is consistent with results in other tumor cell systems." (PMID 24376802, 2013). "It is interesting to speculate that some of the stem cell survival proteins we have localized in skin cancer stem cells, including Oct4, Sox2, Ezh2 and Bmi-1, may provide such targets." (PMID 24376802, 2013).
tongue cancer (5 papers, 2013 to 2024). A malignant neoplasm affecting the tongue. "We and others have provided evidence that several members of PcG such as EZH2 and Bmi1 are aberrantly upregulated in tongue cancer and associated with aggressiveness and poor prognosis." (PMID 28228691, 2017). "Our loss-of-function studies in vitro indicated that deregulated EZH2 and its associated pathways were involved in diverse aspects of oncogenic phenotype of tongue cancer cells." (PMID 24345883, 2013). "To further understand the significance of EZH2 overexpression in tongue cancers, we set out to identify the potential associations between EZH2 expression and patients' clinicopathological features." (PMID 24345883, 2013). "We found that aberrantly overexpressed EZH2 was associated with pathological grade, cervical nodes metastasis and Ki-67 expression in tongue cancers." (PMID 24345883, 2013). "In the present study, we provide evidence that EZH2, the key catalysis enzyme for H3K27me3, is abnormally overexpressed in a large fraction of tongue cancers." (PMID 24345883, 2013). "Taken together, our results indicate that EZH2 serves as a key driver with multiple oncogenic functions during tongue tumorigenesis and a new biomarker for tongue cancer diagnosis and prognostic prediction." (PMID 24345883, 2013). "Collectively, our findings suggest that EZH2 plays essential roles in maintenance of tongue cancer cells with stem cell properties." (PMID 24345883, 2013). "Then the biological roles responsible for EZH2 in tongue cancer progression were identified using both pharmacological and siRNA-mediated genetic approaches." (PMID 24345883, 2013). "Collectively, these data indicate that EZH2 is aberrantly overexpressed in a significant fraction of tongue cancers." (PMID 24345883, 2013). "The siRNA-mediated knockdown strategy was exploited to delineate the phenotype changes after endogenous EZH2 was specifically inhibited in tongue cancer cells." (PMID 24345883, 2013). "The clinicopathological significance of EZH2 overexpression in tongue cancers prompt us to further dissect the possible biological roles of EZH2 during cancer progression by loss-of-function assays via both pharmacological and genetic approaches." (PMID 24345883, 2013). "Our data indicated that EZH2 downregulation significantly inhibited the invasion and migration properties of tongue cancer cells." (PMID 24345883, 2013). "Our data further extended and confirmed the aberrant overexpression patterns of EZH2 in tongue cancers." (PMID 24345883, 2013). "Noticeably, the positive correlation between EZH2 overexpression and cervical lymph nodes metastasis further strengthened the finding that EZH2 enhanced cell invasion and migration, probably partially via modulation of E-cadherin in tongue cancers." (PMID 24345883, 2013). "As expected, our data from DZNep therapy in tongue cancer xenograft model indicated that DZNep delivery efficiently depleted intratumoral EZH2, significantly inhibited the tumor growth by reducing cell proliferation and triggering cell apoptosis." (PMID 24345883, 2013). "Collectively, these results indicate that DZNep is a robust chemical inhibitor against EZH2 through triggering proteosome-mediated protein degradation and has capacity to modulate EZH2-mediated downstream signaling cascade in tongue cancer cell." (PMID 24345883, 2013). "Elevated EZH2 correlated with shorter overall survival and showed significant and independent prognostic importance in patients with tongue cancer." (PMID 24345883, 2013). "Taken together, these findings strongly suggest that the EZH2 serves as a potent oncogenic regulator involving multiple properties of tongue cancer cells and DZNep executes its anticancer functions, at least in part by its pharmacological inhibition of EZH2 in tongue cancer cells." (PMID 24345883, 2013).
tongue cancer (continued). "To determine whether the inhibitory effects of DZNep on EZH2 expression exist in tongue cancer cells, we first measured the EZH2 abundance change following various concentrations and time courses of DZNep treatment." (PMID 24345883, 2013). "In conclusion, our results indicate that EZH2 serves as a key oncogenic driver during tongue cancer progression and functions as a novel biomarker for diagnosis and prognostic prediction for patients with tongue cancers." (PMID 24345883, 2013). "Therefore, in the present study, we first examined the EZH2 expression and its clinicopathological significance in tongue cancer cell lines and clinical samples." (PMID 24345883, 2013). "Owing to the key roles of EZH2 as multi-faceted regulator of somatic stem cells and cancer, it's plausible to speculate the potential roles of EZH2 in tongue cancer stem cell maintenance." (PMID 24345883, 2013). "However, further in-depth investigations into the molecular mechanisms behind the EZH2 roles in tongue cancer stem cell homeostasis are warranted." (PMID 24345883, 2013). "We anticipate that pharmacological and genetic disruption of EZH2 and its signaling cascade may represent a novel therapeutic strategy against tongue cancers." (PMID 24345883, 2013). "Furthermore, intratumoral EZH2 inhibition induced by DZNep intraperitoneal administration significantly attenuated tumor growth in a tongue cancer xenograft model." (PMID 24345883, 2013). "Taken together, our data provide validation of EZH2 as a potential therapeutic target for tongue cancer treatment and suggest that pharmacological abrogation of EZH2 by native and synthetic chemical compounds might hold great promise as a new therapeutic strategy against cancer." (PMID 24345883, 2013). "Overexpression of EZH2 and downregulation of H19 completely reversed H19 silencing-mediated inhibition of β-Catenin and GSK-3β activation in tongue cancer cells." (PMID 33052244, 2020). "Therefore, our results together with previous studies indicate that aberrant EZH2 overexpression might be one of the pivotal events during the tongue tumorigenesis and EZH2 might be a novel and critical biomarker for diagnosis and prognostic prediction of patients with tongue cancers." (PMID 24345883, 2013). "EZH2 protein was remarkably upregulated in tongue cancers as compared to adjacent non-tumorigenic tissue." (PMID 24345883, 2013). "To further examine EZH2 expression in clinical specimens, we next compared its abundance among three pairs of tongue cancer and adjacent non-tumorigenic tissue." (PMID 24345883, 2013).
autism (4 papers, 2022 to 2025). Persistent deficits in social interaction and communication and interaction as well as a markedly restricted repertoire of activity and interest as well as repetitive patterns of behavior. "The results of this study also revealed the important function of EZH2 in the early morphological development of astrocytes and, for the first time, associated its loss with morphological changes in the development of the nervous system, damage to the BBB function and autism‐like behaviours." (PMID 40022506, 2025). "Future research should examine whether restoring Ezh2 function or targeting the MAPK/ERK pathway could effectively reverse BBB damage and autism‐like behaviours observed in the Ezh2cKO mouse model." (PMID 40022506, 2025).
childhood cancer (4 papers, 2012 to 2023). "The childhood cancer incidence for EZH2 mutation carriers in this study was thus 9% (3/34)." (PMID 28475857, 2017). "In this study, we report that EZH2 was detected by immunohistochemistry in nearly all the investigated HCCs, CCs, hepatoblastomas, metastatic liver tumors and several other childhood cancers." (PMID 22809481, 2012). "They reported that EZH2 was detected by immunohistochemistry in nearly all the investigated HCC, CC, hepatoblastoma, metastatic liver tumors and several other childhood cancers." (PMID 23111165, 2012).
colorectal adenocarcinoma (4 papers, 2016 to 2024). The most common type of colorectal carcinoma. "Our in silico analysis of normal small intestine and colorectal adenocarcinoma gene expression data confirms that EZH2 expression is inversely correlated with miR-200, the human homolog of miR-8." (PMID 38429303, 2024). "The types and sites of EZH2 genetic mutations were noted throughout the whole amino acid sequence, and the E745k site with the highest alteration frequency was detected in four cases of UCEC, one case of STAD, and one case of colorectal adenocarcinoma." (PMID 36545914, 2023).
diabetic retinopathy (4 papers, 2017 to 2024). "Increased EZH2 expression and activity have been reported in high glucose-stimulated retinal endothelial cells and are linked to dysregulation of miR-200b and diabetic retinopathy." (PMID 38580969, 2024). "In addition, transitioning to the human disease, our exciting results show that similar increase in H3K27me3 and Ezh2 is also observed in the retinal microvessels from human donors with diabetic retinopathy." (PMID 29261844, 2017). "In diabetic retinopathy, ANRIL regulates VEGF through interactions with PRC2 components p300, miR200b, and enhancer of zeste homolog 2 (EZH2)." (PMID 34512715, 2021). "Thus, in the pathogenies of diabetic retinopathy, MMP-9 has a major role in damaging the mitochondria and accelerating the apoptotic machinery, and Ezh2 appears to be critical in maintenance of cellular epigenetic integrity by regulating both histone modifications and DNA methylation." (PMID 29261844, 2017).
esophageal tumor (4 papers, 2015 to 2023). "SOX4 promotes esophageal tumor cell proliferation and invasion by silencing miR-31 via the activation and stabilization of a co-repressor complex with EZH2 and HDAC3." (PMID 34973135, 2023). "Here, we studied the expression of RUNX3 and EZH2 in 58 esophageal tumors along with paired adjacent normal tissue." (PMID 32943993, 2020). "Here, we report that SOX4 promotes esophageal tumor cell proliferation and invasion by silencing miR-31 via activation and stabilization of a co-repressor complex with EZH2 and HDAC3." (PMID 25644061, 2015). "Clinically, compared to normal adjacent tissues, esophageal tumor samples showed an up-regulation of SOX4, EZH2, and HDAC3 in which the EZH2 expression was significantly increased in metastatic ESCC tissues." (PMID 34973135, 2023). "Clinically, when compared to normal adjacent tissues, esophageal tumor samples show upregulation of SOX4, EZH2, and HDAC3, and EZH2 expression is significantly increased in metastatic ESCC tissues." (PMID 25644061, 2015).
hepatoblastoma (4 papers, 2012 to 2025). Hepatoblastoma (HB) is a malignant hepatic tumor and is the most common pediatric liver cancer. "Although hepatoblastomas also express EZH2, the diagnostic significance of this observation seems to be quite limited whereas, the structurally similar, other blastic childhood tumors are also positive." (PMID 22809481, 2012). "Several classes of drugs, including DNMT inhibitors (e.g., azacytidine), HDAC inhibitors, and EZH2 inhibitors, are under investigation in preclinical models and clinical trials for hepatoblastoma." (PMID 39596558, 2024). "Histone methyltransferases (HMTs), such as EZH2, which is overexpressed in hepatoblastoma, add repressive marks like H3K27 trimethylation (H3K27me3) to silence tumor suppressor genes, promoting uncontrolled cell proliferation." (PMID 39596558, 2024). "Again, the number of non hepatoblastomas investigated is quite low, but considering the very consistent positive staining it is highly unlikely that EZH2 could be used to differentiate among these childhood tumors." (PMID 22809481, 2012).
hyperhomocysteinemia (4 papers, 2016 to 2021). A serious metabolic condition caused by mutations in the MTHFR gene, medications, or nutritional deficiency. "During hyperhomocysteinemia, levels of EZH2 are increased as a result of reduced levels of miR-92a and upon OSS, miR-101 expression is downregulated also leading to an increased expression of endothelial EZH2 and the concurrent H3K27Me3." (PMID 33562658, 2021).
Infertility (4 papers, 2022 to 2025). "To clarify the function of EPHX2 in EM‐GCs and EM‐associated infertility, we further overexpressed EZH2 after inducing oxidative stress." (PMID 40827571, 2025). "In summary, we illustrate here that m6A RNA methylation and EZH2/H3K27Me3‐based histone methylation can work together in the deficient decidualization of EM and may contribute to EM‐associated infertility." (PMID 38344897, 2024). "Moreover, we demonstrated in previous research that decreased EZH2 expression and reduced H3K27Me3 levels in EM ovarian granulosa cells can disturb ovulation and lead to EM‐associated infertility." (PMID 38344897, 2024). "Our results demonstrated that miR-22-5p regulates SSCs’ self-renewal by targeting EZH2, which indicated that miR-22-5p may serve as a biological marker for the treatment of infertility caused by cryptorchidism." (PMID 35415251, 2022).
Intellectual Disability syndromes (4 papers, 2019 to 2023). "In line with this, a group of related human developmental overgrowth syndromes, including the Weaver, Weaver-like, Cohen-Gibson, and Overgrowth and Intellectual Disability syndromes, appear to be caused by heterozygous mutations in EED, EZH2 or SUZ12." (PMID 35245348, 2022). "In line with this notion, several related human developmental syndromes, including the Weaver, Weaver-like, Cohen-Gibson, and Overgrowth and Intellectual Disability syndromes, have been linked to heterozygous, usually de novo, mutations in EED, EZH2, or SUZ12." (PMID 30807568, 2019).
Merkel cell carcinoma (4 papers, 2017 to 2024). "Notably, in Merkel cell carcinoma (MCC) tissues, EZH2 exhibited high expression." (PMID 38534385, 2024).
mesenchymal tumors (4 papers, 2020 to 2022). "Loss of function mutations in the BAF SWI/SNF complex that increases the activity of PRC2 further leads to transcriptional repression of antigen presentation and processing genes, potentially rendering mesenchymal tumors sensitive to EZH2 inhibitors." (PMID 36050786, 2022). "EZH2 inhibitors demethylate immune-response and antigen presentation promoter regions, restoring major histocompatibility complex-I expression which could be used as a strategy to sensitize mesenchymal tumors to chemotherapy and immunotherapy." (PMID 36050786, 2022). "Pharmacological inhibition of PRC2 subunits EZH2 or EED restores MHC-I expression and enhances chemotherapy efficacy in murine tumor models, providing a rationale for using PRC2 inhibitors in PD-L1 negative mesenchymal tumors." (PMID 34725325, 2021).